CRTC2 (CREB regulated transcription coactivator 2)
Diseases named in the same sentence as CRTC2 in open-access papers (continued):
Sharing a sentence is not in itself a finding about the gene and the disease.
ovarian carcinoma (4 papers, 2023 to 2025). A malignant neoplasm originating from the surface ovarian epithelium. "We found that CRTC2 was associated with ovarian cancer poor prognosis through Kaplan-Meier database." (PMID 37151390, 2023). "In 110 patients with ovarian cancer, high expression of CRTC2 was associated with poorer prognostic factors and shorter survival." (PMID 37151390, 2023). "CRTC2 is highly expressed in ovarian cancer cells and tissues, and the high expression of CRTC2 is associated with the poor prognosis of ovarian cancer patients." (PMID 37151390, 2023). "In this study, the expression of CRTC2 and the level of autophagy in ovarian cancer cells were increased by time and concentration gradient paclitaxel exposure." (PMID 37151390, 2023). "According to the median method, 110 patients with ovarian cancer were divided into high expression group and low expression group of CRTC2." (PMID 37151390, 2023). "The results showed that only the expression level of CRTC2 in ovarian cancer was negatively correlated with the overall survival of patients [HR=1.54 (1.25-1.89), p < 0.001]." (PMID 37151390, 2023). "To verify the role of CRTC2 in the development of ovarian cancer, we chose to knockdown CRTC2 in SKOV3 cells and overexpress CRTC2 in A2780 cells." (PMID 37151390, 2023). "The expression of CRTC2 in ovarian cancer and its corresponding normal tissues was confirmed by immunohistochemical staining in tissue microarray for the first time." (PMID 37151390, 2023). "Paclitaxel induces the up-regulation of CRTC2 and autophagy level in ovarian cancer cells, thereby promoting the sensitivity of ovarian cancer cells to paclitaxel." (PMID 37151390, 2023). "At the same time, we found that CRTC2 can promote the proliferation and invasion ability of ovarian cancer cells." (PMID 37151390, 2023). "In this study, we demonstrated for the first time that CRTC2 is overexpressed in ovarian cancer and promotes ovarian cancer proliferation and invasion, and demonstrated that its overexpression is significantly associated with poor patient survival." (PMID 37151390, 2023). "Immunohistochemistry was used to detect the expression of CRTC2 in chemotherapy-resistant and chemotherapy-sensitive ovarian cancer tissues." (PMID 37151390, 2023). "Based on this discovery, we tested the effect of paclitaxel, a first-line chemotherapy drug for ovarian cancer, on the knockdown and overexpression of CRTC2 in ovarian cancer cell lines." (PMID 37151390, 2023). "According to the chemosensitivity test, ovarian cancer cells that inhibit CRTC2 are more sensitive to paclitaxel." (PMID 37151390, 2023). "Therefore, CRTC2 has high sensitivity and specificity and can be used as a candidate biomarker for the prognosis of ovarian cancer." (PMID 37151390, 2023). "It has been observed that ovarian cancer patients with high expression of CRTC2 has poor prognosis." (PMID 37953273, 2023). "Subsequently, we found that CRTC2 may affect the chemotherapy sensitivity of ovarian cancer by affecting autophagic flux." (PMID 37151390, 2023). "CRTC2 is over-expressed in chemo-resistant tissues of ovarian cancer." (PMID 37953273, 2023). "In conclusion, we found that CRTC2 gene can promote the development of ovarian cancer." (PMID 37151390, 2023). "Based on this, we have every reason to believe that CRTC2 may induce chemoresistance in ovarian cancer cells." (PMID 37151390, 2023). "Kaplan-Meier analysis was used to demonstrate the relationship between CRTC2 expression and overall survival, confirming that ovarian cancer with high CRTC2 expression had a shorter overall survival, while ovarian cancer with low CRTC2 expression had a longer overall survival (p < 0.001)." (PMID 37151390, 2023). "In summary, we found the expression and function of CRTC2 in ovarian cancer for the first time." (PMID 37151390, 2023). "Therefore, we studied the effect of CRTC2 on the progress of ovarian cancer cells in SKOV3 and A2780 by CCK-8, clone formation, and transwell assays." (PMID 37151390, 2023).
ovarian carcinoma (continued). "We hypothesized that the regulatory effect of CRTC2 on ovarian cancer autophagy is partly attributed to PI3K-AKT signaling pathway." (PMID 37151390, 2023). "We found that CRTC2 was highly expressed in chemoresistant tissues of ovarian cancer." (PMID 37151390, 2023). "In the tissues with high expression of CRTC2, the chemoresistance rate of ovarian cancer was 69.2% (45/65 cases), while in the tissues with low expression of CRTC2, the chemoresistance rate of ovarian cancer was only 44.4% (20/45 cases), and the difference was statistically significant (p = 0.009)." (PMID 37151390, 2023). "The expression of CRTC2 in ovarian cancer was higher than that in the corresponding normal tissues." (PMID 37151390, 2023). "Tissue samples and cell lines were used to investigate the significance of CRTC2 in ovarian cancer." (PMID 37151390, 2023). "CRTC2 may be a potential predictor or target for ovarian cancer therapy." (PMID 37151390, 2023). "Therefore, to our findings, the reason of paclitaxel resistance in ovarian cancer may be the formation of increased CRTC2 and autophagy." (PMID 37151390, 2023). "Next, we explored whether CRTC2 could affect the autophagy level in ovarian cancer cells." (PMID 37151390, 2023). "CRTC3 promotes melanocyte differentiation and tumorigenesis by integrating cAMP and MAPK/ERK signaling, while CRTC2 enhances autophagic flux via PI3K-AKT pathway activation, reducing paclitaxel sensitivity in ovarian cancer cells." (PMID 40977688, 2025). "In contrast, A2780 cells overexpressing CRTC2 had higher IC50 values of paclitaxel, which protected ovarian cancer cells from paclitaxel damage." (PMID 37151390, 2023). "However, the role of CRTC2 in ovarian cancer remains unclear." (PMID 37151390, 2023). "The highly expressed CRTC2 has a tendency of distant metastasis (p = 0.005) and higher FIGO stage (p = 0.018) of ovarian cancer." (PMID 37151390, 2023). "In addition, CRTC2 can affect the expression of PI3K, AKT, autophagic flux and sensitivity to paclitaxel chemotherapy in ovarian cancer." (PMID 37151390, 2023). "However, to our knowledge, the role of CRTC2 in inducing autophagy and paclitaxel resistance in tumors including ovarian cancer has not been reported so far." (PMID 37151390, 2023). "Immunohistochemical staining was used to detect the expression of CRTC2 in 110 cases of ovarian cancer tissues and corresponding normal tissues in tissue microarray, and it was confirmed that the expression of CRTC2 in ovarian cancer tissues was higher than that in corresponding normal tissues." (PMID 37151390, 2023). "Furthermore, our data suggested CRTC2 and ERBB2 behaved as oncogenes in ovarian cancer." (PMID 37845675, 2023).
fatty liver (3 papers, 2019 to 2025). "Notably, in addition to inhibiting lipid synthesis, research has revealed an increase in lipophagy, which can be attributed at least partly to the alleviation of fatty liver symptoms by liver-specific CRTC2 KO." (PMID 41057543, 2025). "An interaction network based on DELs and differential genes (DEGs) suggested that QGD inhibited hepatic steatosis mainly by reducing hepatic insulin resistance and triglyceride biosynthesis via the PPP1R3C/SIK1/CRTC2 and PPP1R3C/SIK1/SREBP1 signal axis, respectively." (PMID 36452137, 2022).
hepatocellular carcinoma (3 papers, 2012 to 2025). A malignant tumor that arises from hepatocytes. "Regarding protein kinase A catalytic subunit alpha (PRKACA), it mediates SIK inactivation and CRTC2-p300–driven transcription, processes linked to hepatocellular carcinoma growth." (PMID 40600138, 2025). "CRTC2 reportedly promotes hepatocellular carcinoma growth through Wnt/β-catenin pathway activation while downregulating the PD-L1/PD-1 axis, thereby enhancing immunotherapy resistance." (PMID 40977688, 2025). "CRTC2 has also been shown to downregulate PD-1/PD-L1, and its knockdown reverses primary resistance to anti-PD-1 therapy in hepatocellular carcinoma." (PMID 40977688, 2025).
Hypoglycemia (3 papers, 2013 to 2020). A decreased concentration of glucose in the blood. "Taken together, our results unveil a novel mechanism by which pro-inflammatory signals intersect with the CRTC2 pathway in liver and this mechanism contributes to the hypoglycemia caused by infection." (PMID 27990298, 2016). "During hypoglycemia, increases in circulating glucagon trigger CRTC2 dephosphorylation in part by increasing its association with CnA at a consensus PXIXIT motif." (PMID 27990298, 2016). "Mice with a CRTC2 defect showed hypoglycemia and maintained better insulin sensitivity when fed a HFD, and the mRNA expression of gluconeogenic genes was significantly decreased in the liver." (PMID 32020874, 2020). "Here we show that in response to endotoxin (LPS) stimulation, inhibition of gluconeogenic gene expression via blocking CRTC2 activation by interleukin-1β (IL-1β) released from macrophage leads to hypoglycemia in mice." (PMID 27990298, 2016). "Thus, TRAF6-mediated inhibition of CRTC2 may serve as a broad mechanism of septic shock-induced hypoglycemia in multiple tissues, which will need further investigation." (PMID 27990298, 2016). "Under hypoglycemia, increases in circulating glucagon promote hepatic glucose production in part through the activation of gluconeogenesis pathway by CREB coactivator CRTC2." (PMID 27990298, 2016). "In the fasted state, glucagon and catecholamines prevent hypoglycemia by stimulating hepatic glycogen breakdown and gluconeogenesis, in part via the cAMP response element binding protein (CREB) and its co-activator CRTC2 (CREB-regulated transcription coactivator 2)." (PMID 24147136, 2013).
melanoma (3 papers, 2019 to 2023). A malignant, usually aggressive tumor composed of atypical, neoplastic melanocytes. "Although the expression of CRTC1 and CRTC2 was observed in cultured melanocytes and/or melanoma cell lines 16, 36, CRTC1 and CRTC2 null mice did not present any skin and coat color changes 5, 6 (and personal communication)." (PMID 34815795, 2021).
cystic kidneys (2 papers, 2016 to 2022). "Taken together, these data demonstrate that CRTC2 is aberrantly enriched in the nucleus and forms nuclear condensates in cystic kidneys." (PMID 35037420, 2022).
autoimmune disease (1 paper, 2017). A disorder resulting from loss of function or tissue destruction of an organ or multiple organs, arising from humoral or cellular immune responses of the individual to their own tissue constituents. "The autoimmune disease modulating ATF/CREB pathway has been shown to promote Th17 differentiation together with CRTC2." (PMID 29231896, 2017).
autoimmune encephalitis (1 paper, 2021). Inflammation of the brain secondary to an immune response triggered by the body itself. "In line with this, Th17 numbers were reduced in CRTC2 knockout mice relative to wild type animals in experimental autoimmune encephalitis and the CRTC2 knockout mice were protected in this model." (PMID 34732767, 2021).
autosomal dominant polycystic kidney disease (1 paper, 2022). Autosomal dominant form of polycystic kidney disease. "This study elucidates a mechanism by which CRTC2 nuclear condensation conveys cAMP signaling to transcription elongation activation and cystogenesis in autosomal dominant polycystic kidney disease." (PMID 35037420, 2022).
cardiac hypertrophy (1 paper, 2025). "For instance, dominant-negative CREB in the heart can cause cardiac hypertrophy, a risk that would be mitigated by specific interaction of hGULF with CRTC2 in the liver." (PMID 40955662, 2025).
cyst (1 paper, 2022). A sac-like closed membranous structure that may be empty or contain fluid or amorphous material. "In addition, immunofluorescence analysis also showed distinct CRTC2 localization patterns, with dispersed cytoplasmic staining in normal kidneys but clear nuclear staining with prominent punctate structures in the cyst‐lining cells in ADPKD mouse kidneys." (PMID 35037420, 2022). "Genetic depletion of CRTC2 suppresses cyst growth in an orthologous ADPKD mouse model." (PMID 35037420, 2022).
depression (1 paper, 2025). "In the hippocampal CA1 region of depression model mice, FXR overexpression may lead to the cytoplasmic translocation of CREB-regulated transcription coactivator 2 (CRTC2), reducing CREB phosphorylation and activity, which in turn lowers BDNF expression." (PMID 40362260, 2025).
diabetic kidney disease (1 paper, 2023). Progressive kidney disorder caused by vascular damage to the glomerular capillaries, in patients with diabetes mellitus. "To explore the expression of CRTC2 in mice with diabetic kidney disease, we measured the expression of CRTC2 in mice with diabetic kidney disease and control mice." (PMID 37884902, 2023). "The effects that were exerted by CRTC2 on epithelial-mesenchymal transition in diabetic kidney disease through the CREB-Smad2/3 signaling pathway were investigated in vivo and in vitro by real-time PCR, WB, IHC and double luciferase reporter gene experiments." (PMID 37884902, 2023). "The results showed that CRTC2 expression was elevated in the kidneys of mice with diabetic kidney disease." (PMID 37884902, 2023). "In summary, we first predicted the potential molecular mechanism by which the glucose and lipid metabolism factor CRTC2 participates in the EMT process in diabetic kidney disease with bioinformatics tools." (PMID 37884902, 2023). "Therefore, CRTC2, which is an important regulator of glucose metabolism, may play a role in the occurrence and development of diabetic kidney disease." (PMID 37884902, 2023).
esophageal cancer (1 paper, 2023). A primary or metastatic malignant neoplasm involving the esophagus. "This CRTC2-CBP/p300-mediated histone modification, links metabolic and epigenetic states to inflammatory potential in esophageal cancer." (PMID 37953273, 2023).
gastric cancer (1 paper, 2014). A primary or metastatic malignant neoplasm involving the stomach. "To investigate whether SIK1 participates in regulation of the CRTC2-CREB axis also in gastric cancer cells, we examined the subcellular localization of CRTC2 protein upon gastrin treatment in AGS-GR cells." (PMID 25384047, 2014).
gestational diabetes (1 paper, 2022). Carbohydrate intolerance first diagnosed during pregnancy. "Unfortunately, there are scarce publications on linking HMGA2, CRTC2 and SLC6A15 genes to gestational diabetes, so further research on this topic needs to be carried out to enable the comparison of our findings presented in this study with other data." (PMID 35454338, 2022).
mucoepidermoid carcinoma (1 paper, 2024). A carcinoma morphologically characterized the presence of cuboidal mucous cells, goblet-like mucous cells, squamoid cells, cystic changes, and a fibrotic stromal formation. "Other reports demonstrated that LINC00473 is downstream of the fusion oncoprotein CRTC1-MAML2 in mucoepidermoid carcinoma, and that the deletion of CRTC2/3 leads to decreased levels of LINC00473." (PMID 38512964, 2024).
pulmonary fibrosis (1 paper, 2022). Chronic progressive interstitial lung disorder characterized by the replacement of the lung tissue by connective tissue, leading to progressive dyspnea, respiratory failure, or right heart failure. "Taken together, these results indicated that SIK2 and the phosphorylation of CRTC2 regulated by SIK2 is involved in the progression of pulmonary fibrosis." (PMID 35410283, 2022). "Our results elucidate a previously unexplored role of SIK2 in pulmonary fibrosis through modulation of CRTC2/ CREB signaling pathway." (PMID 35410283, 2022). "Inhibition of SIK2 significantly attenuated bleomycin-induced pulmonary fibrosis by promoting dephosphorylation and nuclear translocation of CRTC2 and consequently activating the CREB anti-fibrotic pathway." (PMID 35410283, 2022). "Furthermore, the anti-fibrotic activity of ARN-3236 was blocked by the CREB inhibitor 666-15, indicating that inactivation of SIK2 might alleviate pulmonary fibrosis through CRTC2-mediated CREB pathway." (PMID 35410283, 2022).
schizophrenia (1 paper, 2023). A major psychotic disorder characterized by abnormalities in the perception or expression of reality. "In addition, two possible downstream pathways of miR-25-3p, including the SIK1/CRTC2/CREB1 and TWIST1/PI3K/Akt/GSK3β signaling pathways, were examined with the schizophrenic rat model to explore their potential associations with schizophrenia." (PMID 36744005, 2023). "Therefore, an in-depth study is required to further verify the involvement of the SIK1/CRTC2/CREB1 signaling pathway in schizophrenia." (PMID 36744005, 2023). "In conclusion, this study suggests that altered SIK1/CRTC2/CREB1 and TWIST1/PI3K/Akt/GSK3β signaling pathways mediated by miR-25-3p is very likely to be associated with schizophrenia, revealing potential targets for the treatment and clinical diagnosis of schizophrenia." (PMID 36744005, 2023). "This study investigated whether miR-25-3p-mediated SIK1/CRTC2/CREB1 and TWIST1/PI3K/Akt/GSK3β signaling pathways are present in an animal model relevant to schizophrenia." (PMID 36744005, 2023). "Since it was previously reported that CRTC1 is expressed almost exclusively in the hypothalamus and CRTC3 is expressed in adipose tissue, the SIK1/CRTC2/CREB1 signaling pathway was selected and its involvement in the pathophysiology of schizophrenia was investigated in this study." (PMID 36744005, 2023). "In conclusion, the present study suggests that miR-25-3p-mediated SIK1/CRTC2/CREB1 and TWIST1/PI3K/Akt/GSK3β signaling pathways could be potential therapeutic targets for future antipsychotic drugs and candidate diagnosis biomarkers of schizophrenia." (PMID 36744005, 2023).
steatosis (1 paper, 2020). Increased lipid within the cytoplasm of cells. "In conclusion, the present study revealed that SIK1 inhibits hepatic gluconeogenesis and steatosis and that proper regulation of CRTC2 activity by SIK1 kinase is essential for suppressing abnormal hepatic glucose production and lipid storage." (PMID 32020874, 2020).
viral infection (1 paper, 2014). "The observation that diabetic patients are more likely to suffer acute HBV infections than non-diabetic patients supports the contention that metabolic signaling through CRTC2 can influence the outcome of viral infection." (PMID 24529027, 2014).
cancer (38 papers, 2008 to 2025). A tumor composed of atypical neoplastic, often pleomorphic cells that invade other tissues. "At the same time, we also discovered that CRTC2 was positively correlated with cancer malignant indicators such as distant metastasis and FIGO stage." (PMID 37151390, 2023). "CRTC1 and CRTC2 exhibited predominantly faster migrating bands in all six LKB1-null cancer cells, consistent with enrichment of dephosphorylated forms in the setting of LKB1 deficiency." (PMID 34142658, 2021). "Some genes comprising CRRS have been reported to involve the malignant phenotypes in different cancers, such as CRTC2, FBXL22, OPRL1, and PSMA4." (PMID 34862329, 2021). "The overexpression of CRTC2 triggers cancer cell proliferation and metastasis." (PMID 37845675, 2023). "CRTC2 expression was higher in cancer cells than in normal ovarian epithelial cells." (PMID 37151390, 2023). "The CRTC family consists of three members, CRTC1, CRTC2, and CRTC3, which play important roles in metabolism, aging, and cancer." (PMID 34142658, 2021). "Three members of the CRTC co-activator family, CRTC1, CRTC2, and CRTC3, are expressed at varying levels in human lung epithelial and cancer cell lines." (PMID 34142658, 2021). "The mRNA expression of cancer-related molecules, including those within the HGF/MET signaling pathway, were determined by microarray analysis, and compared between non-metastatic CRTC2 and metastatic CRTC2 (liver metastasis: CRTC2-LV)." (PMID 40076928, 2025).